MTOR (mechanistic target of rapamycin kinase)
Diseases named in the same sentence as MTOR in open-access papers (continued):
Sharing a sentence is not in itself a finding about the gene and the disease.
Parkinson disease (127 papers, 2012 to 2026). A progressive degenerative disorder of the central nervous system characterized by loss of dopamine producing neurons in the substantia nigra and the presence of Lewy bodies in the substantia nigra and locus coeruleus. "Metformin has also been found to significantly reduce levels of phospho-Ser129 α-synuclein, a protein associated with Parkinson's disease, through mTOR inhibition and protein phosphatase 2A activation." (PMID 39822457, 2024). "Our specific interest lay in targeting the mTOR enzyme, a molecule that has garnered attention due to its potential associations with Parkinson’s disease." (PMID 38239204, 2023). "Moreover, increased abundance in high fat diet mice has been shown to trigger inflammation by activating the mTOR complex, while it has been associated with Parkinson disease." (PMID 41011443, 2025). "Additionally, TPC2 can associate with the leucine-rich repeat kinase 2 (LRRK2), mutations in which are linked to late-onset Parkinson’s disease, and the mammalian target of rapamycin (mTOR), a serine/threonine protein kinase that when hyperactivated leads to increased growth and proliferation." (PMID 36046356, 2022). "In neurodegenerative diseases, TMAO penetrates the BBB, impairing synaptic plasticity through PERK activation or mTOR pathway inhibition, while promoting Aβ and tau protein aggregation in Alzheimer’s and Parkinson’s disease progression." (PMID 40777990, 2025). "Pathway analysis further showed that the DE proteins were enriched in pathways related to longevity regulating pathways, salmonella infection, Parkinson's disease, Prion disease, AD, autophagy‐related pathways (mTOR signaling pathway, Autophagy), etc.." (PMID 40135197, 2025). "In Parkinson’s disease (PD), elevated mTOR activity in microglia promotes a shift toward pro-inflammatory states, thereby exacerbating alpha-synuclein (α-Syn) aggregation." (PMID 41438470, 2025). "Studies have found that activation of the PI3K/Akt/mTOR signaling pathway can counteract dopaminergic neuronal pyroptosis to alleviate the progression of Parkinson’s disease." (PMID 38020781, 2023). "This highlights the potential therapeutic value of mTOR inhibition for treating Parkinson’s disease." (PMID 37190500, 2023). "These genes were primarily enriched in the “mTOR signaling pathway” and “Parkinson’s disease,” according to the KEGG enrichment analysis." (PMID 37860165, 2023). "As a critical regulator involved in cell metabolism and survival, mTOR has been considered a promising target against Parkinson’s disease." (PMID 37190500, 2023). "The signalling (p38 MAPK and PI3K/Akt/mTOR) pathway can control various events in Alzheimer’s and Parkinson’s disease, viz., neuroinflammation, tau phosphorylation, and synaptic dysfunction." (PMID 37501975, 2023). "SMER28, a small-molecule enhancer of rapamycin (SMER), identified by chemical screening, was shown to induce mTOR-independent autophagy and to reduce mutant Huntington aggregates and A53T α-synuclein in cellular models of Huntington’s and Parkinson’s disease." (PMID 37235339, 2023). "Following induction of Parkinson's, the levels of α-Syn (A) and mTOR(B) were significantly up-regulated compared to the sham group." (PMID 36247500, 2022). "Another study showed that CR (30 mg/kg) alleviated apoptosis, neurodegeneration, and enhanced protection in rotenone-induced Parkinson’s disease rats via mammalian target of rapamycin (mTOR) pathway activation." (PMID 35991882, 2022). "Overexpression of SIRT3 exhibited a protective role in rotenone-induced Parkinson's disease cell model by activating AMPK/mTOR pathway." (PMID 35291946, 2022).
Parkinson disease (continued). "Overexpression of miR‐30b‐5p has also been reported to partially reverse the inhibitory effect of baicalein on the AMPK/mTOR pathway in Parkinson's disease." (PMID 36282532, 2022). "Pathway analyses implicated Alzheimer’s and Parkinson’s diseases (PFDR ≤ 0.024 in SH-SY5Y and HeLa) and amyotrophic lateral sclerosis (ALS, PFDR < 0.05 in mTOR inhibition experiments)." (PMID 36271102, 2022). "In Parkinson’s disease (PD) models, both partial mTOR inhibition and mTOR activation can be neuroprotective to degenerating DA neurons via different mechanisms." (PMID 35881440, 2022). "For instance, the activity of Akt and mTOR is significantly lower in the neurons of patients with Parkinson's disease compared with unaffected individuals." (PMID 33628381, 2021). "AMPK activators, mTOR suppressors, and trehalose have been demonstrated to be effective in animal models of neurodegenerative disorders, such as Alzheimer’s, Parkinson’s, and Huntington’s diseases." (PMID 34341709, 2021). "RTP801 is a negative regulator of mTOR and Akt that is necessary and sufficient for neuron death in Parkinson’s disease (PD)." (PMID 34131105, 2021). "A significant body of data implicates pathologic induction of the gene for REDD1/RTP801 protein in Parkinson's disease, the only function of which as a regulator is to suppress mTOR." (PMID 34215308, 2021). "Recent evidence demonstrated that electroacupuncture can induce neuroprotective effects in AD and Parkinson's disease animals by the regulation of mTOR-independent autophagic clearance." (PMID 32382276, 2020). "Zhou et al16 revealed that epigallocatechin‐3‐gallate reduced apoptosis in substantia nigra neurons in Parkinson's model rats through mTOR/AKT/GSK‐3β activation." (PMID 32108985, 2020). "Suppressing mTOR signaling inhibits neuronal inflammation in traumatic brain injury and Parkinson’s disease." (PMID 33153476, 2020). "Overexpression of miR-185 inhibits autophagy and apoptosis of dopaminergic neurons by regulating the AMPK/mTOR signaling pathway in Parkinson’s disease." (PMID 33013313, 2020). "The following RT2 Profiler PCR Arrays were used for cDNA quantification: Mouse mTOR Signaling, Mouse Parkinson’s Disease Array, and Mouse Cell Death PathwayFinder." (PMID 31531390, 2019). "For the treatment of Parkinson`s disease (PD), several natural compounds, like curcumin derived from the curry spice turmeric, were shown to downregulate mTOR signaling." (PMID 30609721, 2019). "Functional studies of Parkinson’s disease genes indicate that the mTOR (mammalian target of rapamycin) pathway probably has a major bearing on neurodegeneration." (PMID 26245297, 2015). "In multiple models of neurodegenerative disease such as Alzheimer’s and Parkinson’s Diseases, inhibition of mTOR phosphorylation by rapamycin is correlated with improved neuronal viability." (PMID 23861877, 2013). "Moreover, in the mTOR-MAPK signaling model for parkinsonism-T2DM, we observed higher glycolysis activity and an increase in the inactivated form of RHEB, and the activation of anaerobic glycolysis." (PMID 39429779, 2024). "Moreover, crocin improved the synaptic plasticity of mPFC by activating mTOR and then ameliorated depressive-like behaviors in Parkinson’s disease mice." (PMID 39065694, 2024). "To determine how eEF1A2 may play a role in the Akt/mTOR signaling pathway in this Parkinson's disease model, we performed eEF1A2 silencing in SH-SY5Y cells before MPP+ treatment." (PMID 37051183, 2023). "Additionally, it has been demonstrated that rapamycin, an mTOR inhibitor, improves motor function and attenuates oxidative stress-related protein damage in a mouse model of Parkinson’s disease." (PMID 38020781, 2023). "The RAS/PI3K/AKT pathway may promote neuronal survival, while the PI3K/AKT/mTOR pathway shows changes in AD, Parkinson’s disease, Huntington disease." (PMID 36875704, 2023).
Parkinson disease (continued). "Previous studies have shown that activated mTOR could promote activation of the NF-κB signaling pathway in neuro-inflammation of Parkinson’s disease and in an in vivo obstructive sleep apnea (OSA) model." (PMID 35506423, 2022). "Thus, it has been suggested by many authors that autophagy upregulation, either by mTOR-dependent or mTOR-independent pathways, can be a potential therapeutic strategy for alleviating Parkinson’s disease." (PMID 34830158, 2021). "The nuclear envelope component proline-rich protein 14 (PRR14) is involved in the nuclear morphological alteration and activation of the mTOR (mammalian target of rapamycin) signaling pathway, and has been repeatedly shown to be upregulated in patients with Parkinson’s disease (PD)." (PMID 33001354, 2021). "Interestingly, the mTOR pathway has also been related to Parkinson’s Disease whereas autophagy regulation had an impact on social behavior in autism spectrum disease mouse models with hyperactive mTOR." (PMID 34801069, 2021). "In Parkinson’s disease, mTOR inhibition may provide cytoprotection for post-mitotic neurons that attempt to enter the cell cycle." (PMID 32066462, 2020). "Moreover, TIPE1 decreases mTOR phosphorylation by stabilizing TSC2 protein in a Parkinson's disease model." (PMID 31179241, 2019). "The phosphatidylinositol-3-kinase (PI3K)/protein kinase B (Akt)/mammalian target of rapamycin (mTOR) pathway plays a vital regulatory role in the occurrence and development of oxidative stress, and the role of oxidative stress in Parkinson’s disease is related to this pathway." (PMID 30611190, 2019). "Finally, O-GlcNAcylation regulation of the PI3K/AKT/mTOR signaling pathway can indirectly modulate aggregation of neuronal proteins, such as Tau and α-synuclein that are involved in AD and Parkinson's disease, respectively, as well as in neuronal cell death." (PMID 30356686, 2018). "Emerging evidence now indicates that mTOR and autophagy are critical aspects of the pathogenesis of Parkinson disease, suggesting that deregulation of Minar2-mediated mTORC1 activity could, in part, also account for the observed impaired motor function in Minar2 KO mice." (PMID 37245847, 2023). "Furthermore, balancing mTOR signaling activity is crucial for autophagy sufficiency and cellular responsiveness to IIS stimulation, which then points toward the pathogenesis and risk management of later-life Alzheimer’s and Parkinson’s diseases." (PMID 37627294, 2023). "Moreover, by activating the AMPK/mTOR pathway, metformin is a potential therapeutic for other neurological diseases, such as Parkinson’s disease (PD) and Huntington’s disease, through enhancing neuronal bioenergetics, protecting nerve repair and reducing toxin protein aggregates." (PMID 36484892, 2022). "Importantly, miR-7 may slow Parkinson’s disease progression and regulate proliferation and the mTOR pathway." (PMID 30993031, 2019). "We discuss how central metabolic sensors like AMPK, mTOR, and HIF-1α oversee these metabolic shifts in response to disease-targeted pathologies in Alzheimer’s, Parkinson’s, Multiple Sclerosis, ischemic stroke, and traumatic brain injury." (PMID 41288829, 2025). "In Parkinson’s disease, it partly steer microglial polarization towards M2 phenotype through the AKT/mTOR pathway, thereby curbing inflammation." (PMID 39537618, 2024). "However, the fine-tuning of mTOR activation may be necessary during Parkinson’s disease." (PMID 37190500, 2023). "In mouse models of Parkinson’s disease, treatment of L-DOPA activates mTOR complex one, which is involved in neural synaptic rehabilitation directed toward the basal ganglia, proving to be a promising therapeutic approach for future clinical trials of PD." (PMID 30223579, 2018).
Parkinson disease (continued). "Based on experimental models of Parkinson’s disease (PD), it has been proposed that at early stages of the disease, stress-induced RTP801 upregulation contributes to mTOR repression, in an attempt to maintain cell function and viability." (PMID 25324725, 2014). "Parkinson’s disease models have found the blockade of the mTOR pathway to be beneficial, as α-synuclein aggregates were not recognised as a major trigger of the pathology." (PMID 39684549, 2024). "In Parkinson’s models, MANF manages cellular stress via endoplasmic reticulum regulation and activates antioxidant pathways through PI3K/Akt/GSK3β and AMPK/mTOR pathway to enhances mitochondrial function." (PMID 37751132, 2023). "CBD stimulates neuronal survival in models of Parkinson’s disease via the protein kinase B/mammalian target of rapamycin (AKT/mTOR) pathway through a mechanism involving TRPV1 and can also induce cancer cell death by inhibiting AKT/mTOR." (PMID 34046425, 2021). "Disruption of the molecular signals in Akt/mTOR- and MEK/ERK-dependent pathways may severely affect the development of Parkinson's disease." (PMID 33628381, 2021). "When we compared the Z-scores obtained from these two TWAS, we found that 12 genes discovered in International Parkinson Disease Genomics Consortium (IPDGC) cohort (e.g., MAPT, SNCA, ATG14, DVL3, and MTOR) could be replicated." (PMID 30824768, 2019). "Additionally, PTEN dysfunction is associated with clinical conditions such as autism spectrum disorder, Alzheimer’s and Parkinson’s diseases, and macrocephaly, highlighting its critical and complementary role within the PI3K/Akt/mTOR signaling pathway in neurons." (PMID 40358185, 2025). "A lot of evidence indicates that salidroside inhibits neurocyte apoptosis to protect against Parkinson’s disease, and that it reduces brain cell apoptosis to improve long-term behavioral and histological outcomes that are realized by suppression of phosphorylation of PI3K, Akt, and mTOR." (PMID 29636693, 2018). "This may also explain why genetic ablation of MTOR does not phenocopy rapamycin, and why Torin, a much stronger mTORC1 inhibitor that does not activate TRPML1 22, lacks protective effects on neuron death in in vivo models of Parkinson disease." (PMID 40395298, 2023).
metabolic syndrome (121 papers, 2009 to 2026). A cluster of metabolic risk factors for CARDIOVASCULAR DISEASES and TYPE 2 DIABETES MELLITUS. "For instance, corticosteroids and calcineurin inhibitors heighten the risk of PTDM, while mTOR inhibitors are strongly associated with dyslipidemia." (PMID 40142909, 2025). "Dyslipidemia and hypertension occur in 40-70% of recipients, and are usually associated with the use of mammalian target of rapamycin (mTOR) inhibitors and calcineurin inhibitors." (PMID 36843576, 2023). "The long-term impact of mTOR inhibition on cardiovascular risk is unclear, as findings of reduced cardiovascular risk in patients on mTOR inhibitors are confounded by more frequent use of lipid lowering therapy in response to dyslipidemia." (PMID 36017084, 2022). "Other adverse events often associated with mTOR inhibitor therapy, including proteinuria and dyslipidemia, rarely led to everolimus discontinuation." (PMID 36555914, 2022). "Recently, it has been suggested that activation of mTOR pathways plays an important role in liver tumorigenesis associated with metabolic syndrome and NASH." (PMID 31614491, 2019). "It was demonstrated that upstream regulators associated with the mammalian target of rapamycin (mTOR) pathway were altered in liver tumors of mice with metabolic syndrome characteristics (TSOD mice) using proteome analysis." (PMID 30469530, 2018). "The rate of strong p-mTOR expression was much higher in metabolic syndrome/NASH-associated HCCs than that in virus-associated HCCs." (PMID 30469530, 2018). "mTOR was overexpressed in more than half of metabolic syndrome/NASH-associated HCCs and virus-associated HCCs." (PMID 30469530, 2018). "p-mTOR expression was high in 63% of metabolic syndrome/NASH-associated HCCs, but only in 3% of virus-associated HCCs." (PMID 30469530, 2018). "In the present study, we revealed upstream regulators associated with the mTOR pathway to be altered in liver tumors of NASH model mice with metabolic syndrome (TSOD mice) using QSTAR Elite LC-MS/MS and IPA analyses." (PMID 30469530, 2018). "To apply the results of NASH mouse models to human HCCs, we performed the immunohistochemical evaluation of mTOR in metabolic syndrome/NASH-associated HCCs and virus-associated HCCs in human." (PMID 30469530, 2018). "It was revealed that the mTOR pathway is also characteristically activated in human HCCs associated with metabolic syndrome and NASH." (PMID 30469530, 2018). "Interestingly, the dysfunctional AKT/mTOR pathways associated with enhanced glucose metabolism is considered important factors linking the psoriatic keratinocyte phenotype to metabolic syndromes." (PMID 40277891, 2025). "We further investigated the potential effect mechanism of CO in HFD-induced dyslipidemia, which is probably closely linked with the metabolism of the lipid, particularly, the mammalian target of the rapamycin (mTOR) signal pathway and gut microbiota-mediated inhibition of lipid synthesis." (PMID 35745155, 2022). "Among calcineurin inhibitors (CNIs), cyclosporine has a greater impact on metabolic and cardiovascular comorbidities than tacrolimus, while the mammalian target of rapamycin (mTOR) inhibitors lower the risk of metabolic syndrome compared to CNIs, except for their impact on fat metabolism." (PMID 35294954, 2022). "Although there is a high incidence of the side effect of dyslipidemia, the anti‐atherosclerotic role of mTOR inhibitors may be associated with an anti‐senescence effect, which seems to be independent of changes in lipids." (PMID 35569818, 2022). "On the other hand, dyslipidemia caused by mTOR inhibitors may be balanced by the cardioprotective effects of these drugs." (PMID 36013220, 2022). "Finally, eleven CpG sites were associated with metabolic syndrome: cg08862778 (MTOR), cg11322849 (INS), cg07199894 (ULK1), cg11658986-cg04149773 (ADCY6), cg14862787-11301281 (CREB5), cg14844401-cg20300093 (ADCY5), cg01284192 (IGF1R) and cg08128650 (RELA)." (PMID 30926763, 2019).